FBLN2 (fibulin 2)
Diseases named in the same sentence as FBLN2 in open-access papers (continued):
Sharing a sentence is not in itself a finding about the gene and the disease.
Cirrhosis (2 papers, 2018 to 2023). A chronic disorder of the liver in which liver tissue becomes scarred and is partially replaced by regenerative nodules and fibrotic tissue resulting in loss of liver function. "Given the role of FBLN2 in cirrhosis and other tumors and the paucity of research in HCC, our study aimed to evaluate the expression of FBNL2 in HCC." (PMID 37162505, 2023).
Down syndrome (2 papers, 2019 to 2020). "In a cohort of patients with Down syndrome and AVSD, variants with the highest probability of being damaging in cases compared to Down syndrome patients without cardiac defects were in the VEGF-A pathway genes COL6A1, COL6A2, CRELD1, FBLN2, FRZB, and GATA5." (PMID 31888141, 2019).
gastric cancer (2 papers, 2021 to 2024). A primary or metastatic malignant neoplasm involving the stomach. "Downregulation of β-catenin, a subunit of the cadherin protein complex and a signal transducer of the Wnt pathway, has been found to be involved in the antitumor effect of FBLN2 in gastric cancer." (PMID 34769264, 2021).
glioblastoma (2 papers, 2022 to 2025). The most malignant astrocytic tumor (WHO grade IV). "However, while we observed an increase of fibulin-2 expression in GL261 tumor-bearing mice as compared to sham, fibulin-2 transcriptional expression is frequently downregulated in human glioblastoma." (PMID 36048342, 2022).
hypertrophic cardiomyopathy (2 papers, 2020 to 2025). A condition in which the myocardium is hypertrophied without an obvious cause. "Fibulin 2 levels aresignificantly increased in serum and are abnormally expressed in the myocardiumof hypertrophic cardiomyopathy patients." (PMID 40026492, 2025). "This study shows, for the first time, increased levels of FBLN2 in the myocardium and serum of patients with hypertrophic cardiomyopathy." (PMID 33003281, 2020).
invasive ductal carcinoma (2 papers, 2017 to 2024). "Further, Her2 + and triple-negative patients had a higher expression of FBLN2 compared to LumA and LumB at lesions of invasive ductal carcinoma (IDC), ductal carcinoma in situ (DCIS), and control regions." (PMID 39110274, 2024).
metastatic tumors (2 papers, 2013 to 2020). "Using a public domain dataset (GSE31684), we demonstrated that FBLN2 was a significantly upregulated gene related to the ECM structural constituent and associated with advanced tumor stage and metastatic disease in UBUC." (PMID 33194662, 2020). "In UBUC patients with high FBLN2-expressing tumors, 39.9% had tumor metastasis and 27.0% died of the disease, whereas only 11.6% of patients with low FBLN2-expressing tumors had subsequent metastatic tumors and 8.2% experienced cancer deaths." (PMID 33194662, 2020).
Obesity (2 papers, 2019 to 2025). Accumulation of substantial excess body fat. "For instance, a multi-omics study showed increased expression of FBLN2 in high-fat diet obesity-resistant mice." (PMID 41465472, 2025).
sarcoma (2 papers, 2013 to 2020). A usually aggressive malignant neoplasm of the soft tissue or bone. "A CpG site in the promoter of fibulin 2 (FBLN2) was the most important marker for sarcoma cluster 6 (MPNST samples) compared to sarcoma clusters 1, 3 and 6 (mainly consisting of DDLS, PLS and, MFS/UPS samples)." (PMID 24345474, 2013).
allergic asthma (1 paper, 2025). A asthma with a basis in a pathological type I hypersensitivity reaction. "CIBERSORT analyses further revealed differences in immune cell infiltration associated with FBLN2 expression in allergic asthma patients, particularly in CD8 T cells." (PMID 41458997, 2025). "The GSEA results indicated that the gene set in the low FBLN2 expression allergic asthma group was primarily associated with Influenza A, Hepatitis C, NOD-like receptor signaling pathway, Leishmaniasis, and Measles." (PMID 41458997, 2025). "In our study, FBLN2 demonstrated a high binding affinity for paricalcitol, indicating that this drug may alleviate allergic asthma symptoms by modulating FBLN2-associated immune pathways." (PMID 41458997, 2025). "Allergic asthma patients with high FBLN2 expression exhibited a higher proportion of CD8 T cells compared to those with low FBLN2 expression." (PMID 41458997, 2025). "This study highlights the roles of OBSCN and FBLN2 in immune regulation in allergic asthma, suggesting midecamycin and paricalcitol as potential therapeutic agents." (PMID 41458997, 2025). "Finally, potential drug interactions between OBSCN and midecamycin, as well as between FBLN2 and paricalcitol, were explored through molecular docking analysis, offering new insights for the precision treatment of allergic asthma." (PMID 41458997, 2025). "In this study, we screened the DEGs between allergic asthma patients and healthy controls using a bioinformatics approach and ultimately identified 2 core genes, OBSCN and FBLN2, by integrating WGCNA, machine learning, and PPI network analysis." (PMID 41458997, 2025). "In this study, we identified FBLN2 and OBSCN as core genes in allergic asthma through bioinformatics analysis, machine learning, and molecular docking." (PMID 41458997, 2025). "To further elucidate the roles of FBLN2 and OBSCN in allergic asthma, we conducted single-gene GSEA for each of the 2 core genes and visualized the top 5 upregulated and downregulated pathways." (PMID 41458997, 2025). "Our findings suggest that FBLN2 and OBSCN could serve as potential biomarkers and therapeutic targets for allergic asthma, highlighting their potential in its diagnosis and treatment." (PMID 41458997, 2025). "The expression levels of OBSCN and FBLN2 exhibited significant positive and negative correlations with the proportions of various immune cells, further confirming their potential role in allergic asthma through modulation of the immune microenvironment." (PMID 41458997, 2025).
atrioventricular septal defects (1 paper, 2021). "In humans, FBLN2 variants have been associated with atrioventricular septal defects and intracranial aneurysm, providing additional support for a role in vascular remodeling." (PMID 33971972, 2021).
cholangiocarcinoma (1 paper, 2025). A carcinoma that arises from the intrahepatic biliary tree (intrahepatic cholangiocarcinoma) or from the junction, or adjacent to the junction, of the right and left hepatic ducts (hilar cholangiocarcinoma). "Among these cancer genes, KLF4 suppresses the proliferation of cholangiocarcinoma, while FBLN2 is an independent protective factor for hepatocarcinoma." (PMID 39920810, 2025).
colorectal tumours (1 paper, 2010). "Colorectal tumour lines showed frequent methylation of all 5 genes, whilst prostate tumour lines demonstrated frequent methylation of CIDE-A, DBC1, EMILIN2, SALL1 and less frequent methylation for FBLN2." (PMID 20205715, 2010).
COVID-19 (1 paper, 2025). A disease caused by infection with severe acute respiratory syndrome coronavirus 2. "In contrast, the gene set in the high FBLN2 expression group was primarily associated with Ribosome, Coronavirus disease - COVID-19, Spliceosome, Primary immunodeficiency, and Oxidative phosphorylation." (PMID 41458997, 2025).
demyelination (1 paper, 2024). "Adeno-associated virus deletion of FBLN2 in astrocytes improved oligodendrocyte numbers and functional recovery in EAE and generated new myelin profiles after lysolecithin-induced demyelination." (PMID 38743490, 2024).
diabetic retinopathy (1 paper, 2016). "Whereas no specific role for Fbln1 has been described so far in the retina, Fibulin2 (Fbln2) has been implicated in retinal detachment observed in diabetic retinopathy, retinopathy of prematurity and other retinal complications." (PMID 26918849, 2016).
ductal carcinoma in situ (1 paper, 2021). "However, weak to strong fibulin-2 staining was also observed in the periphery of ductal carcinoma in situ (periductal staining), and in a few normal vessels and benign ducts in the tumour surroundings." (PMID 33836007, 2021).
experimental autoimmune encephalomyelitis (1 paper, 2024). An autoimmune demyelinating disease of the central nervous system that is produced experimentally in animals by the injection of homogenized brain or spinal cord in Freund's adjuvant. "Focusing on MS, the inhibitory role of FBLN2 was suggested in the experimental autoimmune encephalomyelitis (EAE) model, in which genetic FBLN2 deficiency improved behavioral recovery by promoting the maturation of oligodendrocytes and enhancing remyelination." (PMID 38743490, 2024).
gastric tumor (1 paper, 2025). "In GC, Integrin beta-like 1 (ITGBL1) via the Akt/Fibulin-2 axis (FBLN2) can enhance the metastatic capacity of the gastric tumor cell by determining AR." (PMID 40664635, 2025).
glomerulosclerosis (1 paper, 2022). A hardening of the kidney glomerulus caused by scarring of the blood vessels. "In addition to vinculin enhancement in KI mice, we also identified the increased expression of ECM proteins (collagen I and fibulin 2) and the reduced expression of integrin β1, which were reported to be involved in the process of glomerulosclerosis and primary FSGS, respectively." (PMID 36173685, 2022).
hepatocellular carcinoma (1 paper, 2023). A malignant tumor that arises from hepatocytes. "This research investigated the role of fibulin-2 in hepatocellular carcinoma and explored the possible mechanisms." (PMID 37162505, 2023). "Cell viability assays were used to explore the role of fibulin-2 on proliferation in hepatocellular carcinoma." (PMID 37162505, 2023). "The expression of fibulin-2 in hepatocellular carcinoma was measured by bioinformatic analysis and confirmed by western blot and immunohistochemical staining in cell lines or patients’ samples." (PMID 37162505, 2023). "The results of the study highlighted the potential of fibulin-2 to be utilized as a promising biomarker and therapeutic target for hepatocellular carcinoma." (PMID 37162505, 2023). "In vivo xenograft assessment confirmed that knockdown of fibulin-2 inhibited hepatocellular carcinoma tumor growth." (PMID 37162505, 2023). "Fibulin-2 promoted the proliferation of hepatocellular carcinoma cells in vitro by regulating Ras-MEK-ERK1/2 signaling pathway, whereas knockdown of fibulin-2 incurred the opposite effect on proliferation." (PMID 37162505, 2023). "Fibulin-2 exhibited tumor promotor activities in malignant progression of hepatocellular carcinoma." (PMID 37162505, 2023). "We reported the upregulation of fibulin-2 in most hepatocellular carcinoma tissues and cells lines." (PMID 37162505, 2023).
hypospadias (1 paper, 2018). Hypospadias is the displacement of the urethral meatus on the ventrum of the penis. "We have also identified two rare variants (p.Ala496Thr; p.Ala1202Gly) in the FBLN2 (fibulin 2) gene in two cases with different phenotypes: 46,XY female with inguinal testes/enlarged clitoris and 46,XY male with hypospadias." (PMID 29378665, 2018).
Insulin resistance (1 paper, 2019). Increased resistance towards insulin, that is, diminished effectiveness of insulin in reducing blood glucose levels. "Rho family GTPase 3 (RND3), PARD6A, TLE2, FBLN2, COL4A1, and COL4A2 are novel biomarkers for the development of insulin resistance." (PMID 30678306, 2019).
invasive carcinoma (1 paper, 2018). A carcinoma that is not confined to the epithelium, and has spread to the surrounding stroma. "This was particularly obvious at the interface between normal ducts and tumour tissue, where ductal expression of FBLN2 was lost in regions of DCIS/invasive carcinoma." (PMID 30237579, 2018).
invasive lobular carcinoma (1 paper, 2024). "Based on pathological classification of patients, Fbln2 was significantly downregulated in IDC patients when compared to invasive lobular carcinoma (ILC) (P < 0.0001)." (PMID 39110274, 2024).
juvenile dermatomyositis (1 paper, 2025). Juvenile dermatomyositis (JDM) is the early-onset form of dermatomyositis (DM), a systemic, autoimmune inflammatory muscle disorder, characterized by proximal muscle weakness, evocative skin lesion, and systemic manifestations. "In the RNAseq analysis using formalin-fixed paraffin-embedded (FFPE) skin biopsies from juvenile dermatomyositis and CLE patients, Fibulin-2 was reported to be the most elevated JDM specific protein gene." (PMID 41614843, 2025).
kidney cancer (1 paper, 2015). Primary or metastatic malignant neoplasm involving the kidney. "Thus, the changes we identified in alternative splicing of these genes are appealing potential diagnostic markers for tumor initiation in several cancers, and FBLN2, AP2B1 and TCF20 are also good prognostic markers for patient survival in breast, lung, and kidney cancers, respectively." (PMID 25908786, 2015).
liver cirrhosis (1 paper, 2023). "According to analysis of clinical characteristics, the high expression of FBLN2 was significantly correlated with liver cirrhosis history." (PMID 37162505, 2023).
lung squamous cell carcinoma (1 paper, 2021). "Primary lung squamous cell carcinoma expressed significantly more FBLN2 protein compared to adenocarcinoma (p = 0.047)." (PMID 34769264, 2021).
lung tumors (1 paper, 2018). "However, expression levels of downstream markers TPM-1, TOM-1, CRK, fibulin-2, MIF, and EFNA-3 were greater in the lung tumors than in non-tumor specimens only in patients without COPD." (PMID 29371906, 2018).
lupus (1 paper, 2025). "Four proteins, SNRPB/SNRPN, OGN, IFI27, FBLN2, identified only in extracellular vesicles in the blood of CLE patients were also proteins reported to be related to lupus and inflammation." (PMID 41614843, 2025).
lymph node metastasis (1 paper, 2020). "In addition, high FBLN2 expression was significantly associated with adverse pathologic tumor characteristics, such as advanced pathologic tumor stage, high histological tumor grade, lymph node metastasis, VI, PNI, and high mitotic rate." (PMID 33194662, 2020). "Following univariate analysis, we observed that advanced pT status, lymph node metastasis, high histological grade, VI, PNI, high mitotic activity, and high FBLN2 expression (all p < 0.0001) were associated with worse DSS and MFS." (PMID 33194662, 2020). "Apart from FBLN2 immunoexpression, we found that tumor location, multifocal tumors pathologic stage, lymph node metastasis, histological grade, PNI, and VI were significant prognosticators of MFS and DSS in the univariate analysis." (PMID 33194662, 2020). "Pearson's chi-square test showed that high FBLN2 immunoexpression significantly correlated with adverse pathologic variables, such as advanced pathologic tumor stage, high histological grade, perineural invasion, vascular invasion, lymph node metastasis, and increased mitotic rate (all p < 0.05)." (PMID 33194662, 2020).
myopia (1 paper, 2020). "Some identified variants showed precise scaling in corneal curvature and eye elongation (i.e. axial length) to maintain eyes in emmetropia (i.e. HDAC11/FBLN2 rs2630445, RBP3 rs11204213); others exhibited association with myopia with little pleiotropic effects on eye elongation." (PMID 32193507, 2020).
osteosarcoma (1 paper, 2017). A usually aggressive malignant bone-forming mesenchymal neoplasm, predominantly affecting adolescents and young adults. "Fibulin-2 degradation has also been associated to tumorigenesis in osteosarcoma." (PMID 28099917, 2017). "In fact, a considerable amount of Fibulin-2 proteolytic products are detected in osteosarcoma cell lines in comparison with primary osteoblasts." (PMID 28099917, 2017).
prostate tumours (1 paper, 2010). "FBLN2 demonstrated tumour specific methylation in prostate tumours (36%) and was unmethylated in lung tumours." (PMID 20205715, 2010).
pterygium (1 paper, 2021). A wedge-shaped fibrovascular lesion arising from the bulbar conjunctiva and extending to the cornea. "The expression of mRNA in healthy patients was very similar to that of FBLN2; however, in pterygium, the expression was decreased approximately 1.5 times as compared with that of healthy samples (p < 0.05)." (PMID 34945227, 2021). "Our studies have shown that a significant increase in FBLN2 expression generally occurred in the subepithelial tissue of pterygium." (PMID 34945227, 2021).
squamous cell carcinoma (1 paper, 2021). A carcinoma arising from squamous epithelial cells. "In primary tumor tissues, positive staining of fibulin 2 was found in 46.2% (24/52) of adenocarcinoma (ADC) and 66.7% (28/42) of squamous cell carcinoma (SCC), and this difference was statistically significant." (PMID 34769264, 2021).
thoracic aortic aneurysm (1 paper, 2020). An aneurysm formed in the wall of the proximal portion of the descending aorta proceeding from the arch of the aorta. "During cardiovascular disease, FBLN2 has also been identified in the wall of the aorta, contributing to the ECM pool and mediating changes in the aortic wall structure upon injuries, such as thoracic aortic aneurysm." (PMID 33003281, 2020).